FGF2 (fibroblast growth factor 2)
Diseases named in the same sentence as FGF2 in open-access papers (continued):
Sharing a sentence is not in itself a finding about the gene and the disease.
cancer (continued). "Indeed, M2 macrophages could be efficient promoters of FGF-2-dependent proliferation of adjacent cancer cells." (PMID 35954218, 2022). "Using conditioned medium from TNBC cells stimulated with FGF2, we have also ascertained that the paracrine activation of the S100A4/RAGE pathway triggers angiogenic effects in vascular endothelial cells (HUVECs) and promotes the migration of cancer-associated fibroblasts (CAFs)." (PMID 33946884, 2021). "The ds-Diabody targeting FGF-2 may provide an effective strategy for cancer therapy." (PMID 33718141, 2021). "While FGF2 signaling through secreted FGF2 is well understood, the cellular functions and molecular mechanisms of nuclear FGF2 have not been well studied, even though upregulation of nuclear FGF2 is highly correlated with poor prognosis and metastasis in cancers." (PMID 32383752, 2020). "Moreover, FGF2 and FGFRs may also play an essential role in anti-angiogenic therapy resistance in cancer." (PMID 33121202, 2020). "Dosing FGF2 serum levels may provide an indirect, non-invasive way to monitor cancer progression." (PMID 32456056, 2020). "Further analysis of WES data revealed additional variants in common cancer‐related genes involved in DNA replication and DNA damage (e.g., ATM, CDKN1A), cell polarization (SCRIB), proliferation (RNASEL), VEGF expression (MAP3K1, MAP3K6), and in genes encoding growth factors (FGF2) (Table EV2)." (PMID 32667137, 2020). "CSCs could be enriched by culturing primary or developed cancer cell lines in medium with serum reduction and the presence of growth factors such as EGF and FGF2, in which cancer cells form spheres and become more capable of tumorigeneicity and resistant to chemotherapy." (PMID 31928533, 2020). "Based on the function of Src in the migration and invasion of cancer cells, FGF-2 may increase the migration ability as well as the proliferation ability of hASCs, and we will continue to conduct further research on the safety and utility of hASCs for clinical application." (PMID 31775870, 2019). "Therefore, elucidation of the molecular mechanisms of FGF2 action during End‐MyoT and End‐N‐MyoT may eventually contribute to the development of therapeutic strategies for cancer and other pathological situations." (PMID 31094056, 2019). "Because FGF2 is an activator of mitogenic signaling pathways, we hypothesized that the toxicity induced by this growth factor in cancer cells might also intensify the mobilization of stress pathways, further increasing their dependency on these pathways for cell viability." (PMID 30422399, 2019). "Therefore, by sustaining MAPK‐ERK1/2 overactivation, a signaling pathway frequently overridden in malignant transformation, FGF2 reinforces the dependence on stress‐response pathways, increasing the toxicity of stress‐targeted therapeutic inhibitors in both murine and human cancer cells." (PMID 30422399, 2019). "FGF2-based dual warhead conjugate not only kills cancer cells more efficiently than single drug conjugates, but also has the potential to limit the ability of cancer cells to develop resistance to cytotoxic drugs, which is a well-known feature of various cancers." (PMID 30029518, 2018). "Thus, targeting the FGF-2 signaling pathway may have profound implications for cancer treatment, drug sensitivity, and possible metastasis." (PMID 29423271, 2018). "On this basis, pharmacophore modeling of the interaction of a minimal PTX3-derived FGF-binding pentapeptide with FGF2 has been used for the identification of the first small molecule chemical (NSC12) which acts as an extracellular FGF trap with significant implications in cancer therapy." (PMID 29137286, 2017). "As FGF2-FGFR signaling has been implicated as a central channel in the development of CSC-like phenotypes by API5, we believe that inhibition of FGFR signaling may be an effective strategy to control human cancer." (PMID 28092370, 2017).
cancer (continued). "Moreover, secreted factors (for example, thrombospondin 1 (THBS1) and biglycan (BGN)), and growth factors and cytokines (for example, TGFβ, CXCL12/SDF1, CTGF and FGF2), many of which actively control endothelial and cancer cell behaviour, were differentially regulated between iNFs and iCAFs." (PMID 28198360, 2017). "Moreover, FGF-2 can promote cancer cell invasion and metastasis." (PMID 27918462, 2016). "Therefore, FGF2 functions in an autocrine or paracrine manner in cancer cells." (PMID 27007053, 2016). "Following Cox-2 inhibition, we observed reduced infiltration of tumors with cancer-associated fibroblasts (CAFs) and lower levels of pro-angiogenic factors active besides the VEGF axis including hepatocyte growth factor (HGF) and basic fibroblast growth factor (FGF2)." (PMID 25849942, 2015). "Thus, TGF-β and FGF-2 may cooperate to regulate EMT in various kinds of cells during cancer progression." (PMID 23715860, 2013). "FGF2 may have a role in tumorigenesis and cancer progression through induction of angiogenesis." (PMID 22792137, 2012). "Concomitant inhibition of VEGF- and FGF2-induced EC proliferation and targeting only dividing ECs without affecting the survival of ECs are two properties rendering 6-ME as an attractive molecule for the development of a novel anti-angiogenic intervention in cancer treatment." (PMID 22583931, 2012). "Studies in which VEGF-A, VEGF-C, FGF-2 or other growth factors in this setting are blocked might answer the question of relative importance of one or more of these factors alone or in concert and could be important for further cancer treatment approaches." (PMID 23076721, 2012). "The present data support the view that carcinoma stem cells are intrinsically primed to rapidly repair DNA damage, notably through high constitutive nuclear level of FGF2, and could sustain late protective responses through the stress-induced secreted form of the factor." (PMID 22732006, 2012). "Fibroblast growth factor 2 (FGF2), a multifunctional regulator, has shown to play contradictory roles in cancer progression." (PMID 41594226, 2026). "However, as FGF2 regulates neovascularization by increasing the expression of the glycolysis enzyme HK2 and by promoting the proliferation and migration of endothelial cells, FGF2 may synergize with FGF1 in controlling vascularization in the cancer microenvironment." (PMID 41131959, 2026). "Our previous works and others elucidated that GCS modulates the β-catenin signaling pathway to up-regulate the expression of ABCB1, FGF2, and METTL3 in cancer cells." (PMID 40507922, 2025). "Cancer cells secrete cytokines such as VEGF, endothelin 1, EGF-like domain-containing protein 7 (EGFL7), and fibroblast growth factor 2 (FGF2), which downregulate the expression of endothelial selectins, adhesion molecules, and chemokines." (PMID 40136652, 2025). "Previous studies showed that aberrantly elevated expression of GCS in turn promotes the overexpression of ABCB1, FGF2, and IL6 in cancer cells." (PMID 40507922, 2025). "Increasing evidence has revealed that many factors secreted and produced by TAMs enhance cancer progression, such as EGF, PDGF, CXCL8, MMP9, and FGF2 in the TME." (PMID 40076874, 2025). "It regulates the levels of phosphatase and tensin homologue (PTEN), focal adhesion kinase (FAK), fibroblast growth factor-2 (FGF2), phosphatidyl inositol 3-kinase (PI3K)/Akt and neuropeptide signalling, which are crucial in the progression of cancer." (PMID 40581884, 2025). "Next, the expression profiles of CD44, FGF2, FGF10, KDM6A, FN1, and MMP2 were evaluated using the OcoDB database across different clinical stages, age groups, and racial categories in cancer patients." (PMID 39833941, 2025). "Among most significantly altered genes, we selected FGF2, LY6L, and TRIM46 for further study because their gene products are known to increase the viability and malignant proliferation of cancer cells." (PMID 38600695, 2024).
cancer (continued). "The aim was to examine the relationship between FGF2 and FGFR1 and their impact on mRNA expression of P21 and CCND1, cell cycle status, and cancer stemness characteristics." (PMID 38553760, 2024). "Cancer cells secrete growth factors and cytokines (including IL-6, IL-1β, TGF-β1, TGF-β2, FGF-2, and PDGF), which help in the remodeling of the ECM and the development of the TME in cancer cells." (PMID 39518022, 2024). "Patients with low-to-moderate grade carcinoma had significantly higher expression of FGF1 and FGF2 compared to their counterparts with high-grade tumors." (PMID 39302921, 2024). "Conversely, the proteoglycans in cancer pathway, containing genes which code for matrix metalloproteinases (MMP), WNT signaling molecules, and growth factors such as IGF1 and FGF2, is prominent in bexarotene differential expression analysis but not MSU-42011." (PMID 36901727, 2023). "Once in the TME, TAMs supported cancer development through a variety of signaling pathways such as TGF-β, fibroblast growth factor 2 (FGF2), and vascular endothelial growth factor (VEGF)." (PMID 36776295, 2023). "This miRNA improves the chemosensitivity of cancer cells to TAC by suppressing both vascular endothelial growth factor A (VEGFA) and fibroblast growth factor 2 (FGF2)." (PMID 37510280, 2023). "Our results showed that majority hub genes DCAF7, FGF2, GSK3B, NACC2, and NFIB were highly expressed and (nTPM >19) localised mainly in the nuclei of the cancer cells." (PMID 36468011, 2022). "The cancer cell secretome, which includes factors such as TGF-β, platelet-derived growth factor (PDGF), and fibroblast growth factor 2 (FGF2), recruits stromal cells during tumourgenesis." (PMID 36555218, 2022). "By characterizing the FGF-2 regulated transcriptome in normal and cancer cells, we identified sense and antisense transcripts IER3 and IER3-AS1 that play a critical role in FGF-2 controlled oncogenic pathways." (PMID 36038571, 2022). "FGF2 treatment also modified the structure of HUVEC angiospheres, resulting in a central core of HUVECs surrounded by cancer cells, as observed with E4 + ECs." (PMID 36430649, 2022). "In the course of angiogenesis, factors produced by cancer cells contain VEGF, platelet derived growth factor (PDGF), fibroblast growth factor 2 (FGF-2) and angiopoietins." (PMID 36341388, 2022). "Results from our scRNA-seq analyses identified several potential interactions involving the cancer stem cell marker CD44 with ligands secreted by CAFs such as HGF, HBEGF, FGF2 and LGALS9." (PMID 36273171, 2022). "In cancer stem cells, ADAMDEC1 solubilizes FGF2 to induce FGFR1, upregulating ADAMDEC1 expression to maintain its stemness." (PMID 35379209, 2022). "By direct interaction with VEGF and fibroblast growth factor-2 (FGF-2), CXCL4 inhibits the effect of these angiogenic factors and retards cancer growth." (PMID 35269786, 2022). "Our FGF-2 based transcriptomic analysis of immortalized human embryonic kidney cells HEK293 and cancer cell lines HeLa and BT-549 identified gene regulatory networks that execute their biological functions in normal and neoplastic conditions." (PMID 36038571, 2022). "The membrane protein TMEM240 also negatively regulated several extracellular and membrane proteins involved in cell proliferation, migration, and cancer EMT, such as SDF-1, FGF2, oncostatin M, and MMP2." (PMID 35715741, 2022). "Several of these specialized TME microenvironments are enriched by the pan-cancer survival network, for example HIF1A signaling (p = 4.27 × 10−6; FGF2, IGF2, MMP1, MMP14, MMP3, PIK3R3, SERPINE1, TGFB1)." (PMID 35106465, 2022). "Angiogenesis drives the metastasis of cancer and is mediated by factors such as VEGF, fibroblast growth factor-2 (FGF-2), and platelet-derived growth factor (PDGF)." (PMID 35865534, 2022).
cancer (continued). "Fgf2 accelerates epithelial to mesenchymal transition (EMT) in keratinocytes, a process that is known to occur during cancer development." (PMID 36009225, 2022). "Angiogenic factors screening between AAD-sensitive cancer type and AAD-resistant NPC showed high FGF-2 expression in NPC in both xenograft models and clinical samples." (PMID 35985991, 2022). "Myeloid-derived suppressor cells (MDSCs) release chemokines including IL-6, VEGF, FGF-2 and MMP-9 to promote cancer progression and bone metastasis." (PMID 34831167, 2021). "EVs secreted by cancer cells contain pro-angiogenic mediators, including vascular endothelial growth factor (VEGFA), interleukin-8 (IL-8), interleukin 6 (IL-6) and fibroblast growth factor 2 (FGF2)." (PMID 34283059, 2021). "The aim of the present study was to evaluate PCI of FGF2-saporin (FGF-SAP), a conjugate of FGF2 and saporin, as a strategy to target and achieve cytotoxic effects in cancer cells overexpressing FGFRs." (PMID 34204611, 2021). "Secretion of ligands such as FGF2, PDGF, TGF-β, CSF-1 and CTGF by activated PSCs has been shown to promote cancer cell proliferation and invasion." (PMID 33918004, 2021). "Cancer cell-derived cytokines such as transforming growth factor (TGF)-β1, platelet-derived growth factor, and fibroblast growth factor-2 were reported to be capable of transforming normal fibroblasts to CAFs38–41." (PMID 34108603, 2021). "Such a mechanism is also known for increased angiogenesis in cancer by shed SDC-1 with binding to pro-angiogenic factors such as VEGF, FGF2, insulin-like growth factor 1 receptor—IGFR1 and presenting these growth factors to their respective receptors." (PMID 33562126, 2021). "FGF-SAP is a conjugate of FGF2 and the highly cytotoxic ribosome-inactivating protein (RIP) saporin, which is used as payload to eliminate cancer cells." (PMID 34204611, 2021). "During angiogenesis, cancer cells secrete various pro-angiogenic factors such as VEGF, platelet-derived growth factor, and fibroblast growth factor 2 (FGF-2)." (PMID 33291743, 2020). "Upon cell surface binding, FGF-2/FGFR interaction promotes receptor dimerization, trans-phosphorylation of tyrosine kinase domains, and commonly results in increased cancer cell survival, proliferation, drug resistance, and neoangiogenesis." (PMID 32230722, 2020). "FGF2/FGFR inhibitors are being developed and evaluated as monotherapy or as part of a combination therapy for the treatment of different types of cancer." (PMID 33381388, 2020). "PTTG1 has been shown to transcriptionally activate expression of a wide range of target genes, including c-Myc, FGF-2, cyclin D3, p21, and MMP-2, most of which are critically involved in cancer proliferation and metastasis." (PMID 33250768, 2020). "For the purpose of correlation analysis we have retrieved data on systemic concentrations of IL-1β, IL-4, IL-6, IL-8, IL-12p70, FGF2, G-CSF, GM-CSF, MCP-1, MIP-1α, PDGF-BB, TNFα, and VEGF-A, available for 43 of our cancer patients." (PMID 33020452, 2020). "The mechanism behind FGF2’s action includes the phosphorylation of FRS2 which activates the MAPK and PI3K/Akt signaling pathways in both cancer cells and ECs." (PMID 33121202, 2020). "In the presence of cancer cells, fibroblasts can be activated by cancer or immune secreted TGF-β, FGF-2, HGF, PDGF, and interleukins, as well as reactive oxygen species to become cancer-associated fibroblasts (CAFs)." (PMID 31075118, 2019). "The activation of CAFs can be induced by cytokines secreted by cancer cells, including TGF-β and several RTK signaling ligands such as EGF, PDGF and FGF2." (PMID 31671542, 2019). "In the present study, we attempted to elucidate the roles of FGF2 and Elk1 in the regulation of TGF‐β‐induced End‐MyoT and End‐N‐MyoT of TECs derived from xenograft model of human cancer cells." (PMID 31094056, 2019).
cancer (continued). "Lung tumor cells prefers to use the shorten length transcripts of FGF2 (A) and MAP4K4 (B) compared to para-cancer tissue cells, and knocking-down of CSTF2 expression in H460 cells leads to extended length of transcripts for both FGF2 and MAP4K4 genes." (PMID 31391087, 2019). "More recently, an aberrant increase of IRES-dependent translation of key cancer gene mRNAs has been reported in cancer cells, including the major angiogenic factors FGF1, FGF2 and VEGFA, as well as c-myc and insulin growth factor-like receptor (IGF1R)." (PMID 30791615, 2019). "Here, we report the use of fibroblast growth factor 2 (FGF2) to demonstrate that further mitogenic activation disrupts cellular homeostasis and strongly sensitizes cancer cells to stress‐targeted therapeutic inhibitors." (PMID 30422399, 2019). "Exogenous sulfated carbohydrates like heparin and its mimetic derivatives have long been studied for their competition with HS chains, to break the formation of the FGF2–HS–FGFR1 ternary complex and physiologically disrupt the function of cancer cells." (PMID 31035725, 2019). "The single drug-FGF2 conjugates have no impact on the viability of NCI-H446 cells, whereas the dual warhead-FGF2 conjugate selectively and efficiently kills these FGFR1 positive cancer cells." (PMID 30029518, 2018). "GFs (e.g. connective tissue growth factor; CTGF and fibroblast growth factor-2; FGF2) and cytokines exchange between cancer cells and surrounding PSCs have been proved to be pivotal in metabolic crosstalk." (PMID 29458370, 2018). "We have recently proposed FGF2, natural ligand of FGFRs as an alternative targeting factor for selective delivery of cytotoxic agents into FGFR1-overproducing cancer cells." (PMID 30029518, 2018). "We showed that cell surface presentation of fibroblasts-derived FGF-2 to cancer cells, leads to integrin αvβ5-dependent and SRC-mediated adhesion of cancer cells to fibroblasts, and contact-dependent tumor cell elongation, migration and invasion." (PMID 30065926, 2018). "On the other hand, PSCs stimulate cancer cell proliferation by production of paracrine factors as TGF-β, FGF2, PDGF, and epidermal growth factor (EGF) and inhibit apoptosis." (PMID 30662458, 2018). "FGF2 repressed TGF β-induced EMyoT and enhanced the EMT, conferring greater invasiveness similar to that of activated fibroblasts in cancer cell lines." (PMID 30304871, 2018). "Fibrinogen is an extracellular matrix element and regulates the growth of cancer cells by binding to the vascular endothelial growth factor (VEGF), fibroblast growth factor-2 (FGF-2), and platelet-derived growth factor (PDGF)." (PMID 28154828, 2017). "And FLIP, FGF2, SULF2 and MMP13 are known to be overexpressed in various cancers and downstream of hnRNPK." (PMID 28423622, 2017). "Mesenchyme-derived growth factors known to promote cancer cell proliferation (EGF, FGF1, FGF2, and IGF-1) were expressed in different CAF populations to different levels." (PMID 28649646, 2017). "CAFs also secret fibroblast growth factor-2 (FGF-2)that activates angiogenesis and induces the metastatic capability and invasiveness of the cancer cells." (PMID 28392501, 2017). "FGF2 binds to FGF receptors, thus constituting FGF/FGFR signaling, which is involved in regulating the tumorigenesis and progression of a variety of cancers." (PMID 26655091, 2016). "FGF2-induced activation of FGFR signaling and subsequent activation of PI3K/Akt and ERK1/2 signaling pathways in cancer cells." (PMID 27007053, 2016). "Among them, several genes were related in cancer pathway such as EGFR, RARA, FGF2, FGFR1, FGFR2, FGFR3, KIT, and CCND1." (PMID 27016420, 2016). "In FGF1-stimulated cancer cells, KPNA2 was found a role of bounding to FGF1 and FGF2, and the activation of ERK1/2 was increased through ectopic expression of importin α1, finally accelerating the cancer cell proliferation." (PMID 27611951, 2016).